PDGFRA (platelet derived growth factor receptor alpha)
Diseases named in the same sentence as PDGFRA in open-access papers (continued):
Sharing a sentence is not in itself a finding about the gene and the disease.
ovarian carcinoma (43 papers, 2004 to 2026). A malignant neoplasm originating from the surface ovarian epithelium. "We identified significant high-frequency mutations in the ERCC4, CHEK2, and PDGFRA genes in young patients with ovarian cancer." (PMID 38817903, 2024). "PDGFRα/βhigh CAFs have also been linked to lymph node metastasis and lymphovascular invasion in ovarian cancer and pancreatic cancer and lead to poorer prognosis in breast cancer, ovarian cancer, pancreatic cancer, and lobular breast tumors." (PMID 37143134, 2023). "Increased levels of the second PDGFR isoform, PDGFRα was associated with shorter overall survival of 176 ovarian cancer patients." (PMID 29228656, 2017). "We show that EOC, which comprises the vast majority of human ovarian cancers, is associated with defects in formation of primary cilia that control signaling pathways in ovarian homeostasis such as Hh and PDGFRα signaling." (PMID 23351307, 2012). "PDGFRα expression is associated with a more aggressive phenotype and poor ovarian cancer outcomes." (PMID 30591028, 2018). "Based on these observations, we examined whether the inhibitory effects of DHA on the migration of ovarian cancer cells was linked to the impairment of PDGFRα-mediated EMT signals." (PMID 29387451, 2017). "In contrast, PDGFRA was also identified as overexpressed in a poor prognosis gene expression signature in ovarian cancer and it was suggested that PDGFRA could be associated with the occurrence of an epithelial/mesenchymal transition." (PMID 19849863, 2009). "Taken together, all of these findings demonstrate that DHA targets PDGFRα to inhibit ovarian cancer cell growth, the EMT and cell migration." (PMID 29387451, 2017). "Our initial clinical molecular pathology studies further demonstrated that there is linkage between high PDGFRα expression and advanced disease and metastasis in ovarian cancer patients." (PMID 29387451, 2017). "The quantitative analysis of the IHC staining results revealed that the PDGFRα expression was significantly enhanced in the tumor cells ovarian cancer patients with high metastasis." (PMID 29387451, 2017). "Our clinical study also finds that PDGFRα is overexpressed and positively correlated with high grade and metastasis in human ovarian cancer." (PMID 29387451, 2017). "We also found that there was increased expression of PDGFRα in ovarian cancer patients with high pathobiological grade and metastatic disease compared with their less aggressive counterparts." (PMID 29387451, 2017). "We further examined the correlation of PDGFRα expression levels to the metastasis status of ovarian cancer patients." (PMID 29387451, 2017). "Accumulating evidence from both animal experiments and human clinical studies suggests that PDGFRα is involved in the progression of ovarian cancer." (PMID 29387451, 2017). "Our results demonstrated that DHA, one of the most effective ART derivatives, promoted the degradation of PDGFRα protein and selectively inhibited the growth and migration and EMT of PDGFRα-positive ovarian cancer cells." (PMID 29387451, 2017). "Herein, we report that dihydroartemisinin, one of the most active derivatives of Artemisinin, directly targets platelet-derived growth factor receptor-alpha (PDGFRα) to inhibit ovarian cancer cell growth and metastasis." (PMID 29387451, 2017). "We also believe that the results from the current study will facilitate the discovery of novel DHA-based, PDGFRα-targeting agents for the treatment of ovarian cancer, and possibly for other cancers as well." (PMID 29387451, 2017). "It inhibits the growth of ovarian cancer cells through PDGFRA inactivation, and decreases the secretion of VEGF by epithelial ovarian cancer cells." (PMID 20072701, 2010). "In ovarian cancer, the intraflagellar transport protein IFT20 is upregulated and modulates associated signaling pathways such as Hedgehog (Hh) and Platelet-Derived Growth Factor Receptor Alpha (PDGFRα) signaling." (PMID 38887518, 2024).
ovarian carcinoma (continued). "Besides, the expression levels of PDGFRA and PDGFRB were significantly associated with venous invasion and lymphatic invasion of ovarian cancer." (PMID 36199822, 2022). "DHA could directly target platelet-derived growth factor receptor-alpha (PDGFRα) to inhibit the growth and metastasis of ovarian cancer cells." (PMID 33613116, 2021). "Several target genes of miR-140-5p have been identified, including platelet-derived growth factor receptor A (PDGFRA) in ovarian cancer, insulin-like growth factor 2 mRNA-binding protein 1 (IGF2BP1) in cervical cancer, and YES proto-oncogene 1 (YES1) in gastric cancer." (PMID 30962263, 2019). "Expression of PDGFRα has been reported in ovarian cancers, although the prevalence varies." (PMID 30591028, 2018). "In the present study, we tested the hypothesis that platelet-derived growth factor receptor-alpha (PDGFRα) is a key molecular target for DHA as a selective anti-PDGFRα-positive ovarian cancer agent." (PMID 29387451, 2017). "First, DHA selectively inhibits the growth and migration of PDGFRα-positive ovarian cancer cells." (PMID 29387451, 2017). "A recent study identified a 5-marker panel for early detection of ovarian cancer that includes five serum biomarkers, namely macrophage-stimulating protein alpha, tissue inhibitor of metalloproteinases-4, platelet-derived growth factor receptor alpha (PDGF-R alpha), osteoprotegerin, and CA-125." (PMID 27259239, 2016). "PDGFRα, a cell surface tyrosine kinase receptor for members of the platelet-derived growth factor family, is over-expressed in human serous ovarian tumors and is targeted in clinical trials to treat ovarian cancers." (PMID 24603706, 2014). "Further, we demonstrate that ovarian cancer cells have deregulated Hh signaling and platelet-derived growth factor receptor alpha (PDGFRα) expression and that promotion of ciliary formation/stability by AURA siRNA depletion decreases Hh signaling in ovarian cancer cells." (PMID 23351307, 2012). "In addition, overexpression of PDGFRA is an independent poor prognostic factor in ovarian carcinoma." (PMID 20072701, 2010). "In previous reports, PDGFRA immunopositivity has varied from 5 to 100% of ovarian carcinomas." (PMID 15583695, 2004). "PDGFRA alteration is associated with ovarian cancer but not frequently mutated." (PMID 29321820, 2017). "By virtue of UALCAN analysis, we identified that the protein levels of PDGFRA and PDGFRB were significantly lower in tumor tissues of ovarian cancer than those in normal tissues." (PMID 36199822, 2022). "In ovarian cancer, PDGFB (P < 0.05), PDGFD (P < 0.05), PDGFRA (P < 0.001), and PDGFRB (P < 0.001) had a significant positive correlation with macrophage M2 infiltration, and PDGFA had a negative association with macrophage M1 infiltration (P < 0.01)." (PMID 36199822, 2022). "Despite lower expression in ovarian cancer than in normal tissues, patients with higher PDGFD, PDGFRA, and PDGFRB also had worse OS, PFS, and PPS in ovarian cancer." (PMID 36199822, 2022). "Compared with the respective normal tissues, the mRNA and protein levels of PDGFRA and PDGFRB were substantially lower in tumor tissues of almost all cancer types, including ovarian cancer." (PMID 36199822, 2022). "In line with previous reports, we observed that PDGFRA and PDGFRB were predominantly expressed in the tumor stroma of ovarian cancer but merely expressed in cancer cells." (PMID 36199822, 2022). "Consistently, more intense IHC staining of PDGFRA and PDGFRB was observed in normal ovarian tissues than in tumor tissues of ovarian cancer." (PMID 36199822, 2022).
ovarian carcinoma (continued). "In vitro PDGFRα blockade with IMC-3G3, a specific monoclonal antibody, in combination with docetaxel sensitized HeyA8-MDR ovarian cancer cells and induced apoptosis." (PMID 32962103, 2020). "Specifically, these tumors exhibit dysregulated expression of PDGFRα, VCAM, and Wip1, which were previously reported to be involved in human ovarian cancer." (PMID 24603706, 2014). "In ovarian carcinoma, expression of KIT and PDGFRA protein has been documented, but the frequency and the molecular background of expression are poorly known." (PMID 15583695, 2004). "In ovarian carcinomas, the reported frequency of KIT and PDGFRA expression has been highly variable, and little is known about their molecular background and association with clinical parameters." (PMID 15583695, 2004). "ROC analysis also demonstrated that PDGFD (AUC = 0.995), PDGFRA (AUC = 1.000), and PDGFRB (AUC = 0.997) could be a single significant parameter to discriminate between normal and tumor tissues of ovarian cancer." (PMID 36199822, 2022). "Furthermore, the mRNA levels of PDGFRA and PDGFRB in ovarian cancer patients with venous invasion were higher than those in patients without venous invasion." (PMID 36199822, 2022). "We also utilized GZD856, a PDGFRA and PDGFRB inhibitor which suppresses proliferation of lung cancer, and observed that GZD856 effectively inhibit proliferation, invasion and migration of ovarian cancer cells." (PMID 33731124, 2021). "Similarly, our GSEA analysis also demonstrated a positive correlation between PDGFRα expression and PI3K-AKT signaling pathway activity in ovarian cancer, gastric cancer, and bladder cancer." (PMID 33568640, 2021). "DHA could selectively inhibit the growth and migration of PDGFRα-positive ovarian cancer cells (A2780 and OVCAR3), with significantly decreased effects on PDGFRα-null SK-OV3, OVCAR5 and IOSE144 cells." (PMID 29387451, 2017). "PDGF is expressed in 73% of ovarian carcinomas, while 36% express PDGF-receptor alpha (PDGFRA)." (PMID 20072701, 2010). "KIT and PDGFRA are not ubiquitous proteins, but their expression has also been reported in some epithelial malignancies including in ovarian carcinoma." (PMID 15583695, 2004). "As regards PDGFRA, to our knowledge, no previous reports on ovarian carcinoma exist in the literature." (PMID 15583695, 2004). "Besides, ovarian cancer patients with lymphatic invasion expressed higher mRNA levels of PDGFRA and PDGFRB, even though the difference in PDGFRB had no statistical significance." (PMID 36199822, 2022). "Moreover, the negative correlation between PDGFRα and patient survival was also present in multiple tumors including ovarian cancer, gastric cancer, and bladder cancer." (PMID 33568640, 2021). "Notably, for PDGFRA and PDGFRB, epithelial cell proliferation, epithelial cell migration, positive regulation of cell adhesion, and angiogenesis were also highly enriched, suggesting that PDGFRA and PDGFRB might be critically involved in the metastasis of ovarian cancer." (PMID 36199822, 2022). "The primary ovarian cancer cells OvCa3 A were negative for one of either the CAF markers, PDGFRα, transcription factor Sox2, and CSCs marker CD133." (PMID 38791431, 2024). "Immunohistochemistry analysis of multitumor microarrays has shown that tumoral expression of PDGFRα is detected in NSCLC, colorectal, and ovarian cancer (data not shown)." (PMID 23990866, 2013).
sarcoma (42 papers, 2012 to 2025). A usually aggressive malignant neoplasm of the soft tissue or bone. "Consistent with the loss of PDGFRA expression in the acquired resistant sublines, all of the primary resistant sarcoma cell lines expressed low levels of PDGFRA compared to both parental A204 and G402." (PMID 40781553, 2025). "Epigenetic alterations play a crucial role in the pathophysiology of CSs, and CS markers such as CD133, ALDH, and PDGFRα were detected in various subtypes of sarcomas." (PMID 38730621, 2024). "Tyrosine kinase inhibitors (TKIs) have become a staple in addressing sarcomas like GIST, where mutations in KIT and PDGFRA genes drive tumorigenesis." (PMID 38228904, 2024). "This would also be consistent with the mesenchymal origin of sarcomas, many of which are driven by PDGFRA." (PMID 31881074, 2019). "PDGFRA is expressed in multiple tumor types including various types of sarcoma, both in tumor and stromal cells." (PMID 31331295, 2019). "To investigate the differences between CDK4 amp and CS groups, we identified the PDGFRA target drug responses in nine sarcoma cell lines." (PMID 30598078, 2018). "PDGFRA was overexpressed in 22.1% of the sarcomas, including, 38.5% of angiosarcoma, 33.3% of liposarcoma, 33.3% of fibrosarcoma, 31.8% of Ewing's sarcoma, 30.8% of chondrosarcoma, 27.8% of osteosarcoma, 27.8% of UPS and 18.3% of non-uterine LMS." (PMID 25906748, 2015). "Given that PDGFRA expression was diminished upon acquisition of resistance to the four mTKIs, we sought to determine the expression levels of this receptor across the panel of 12 sarcoma cell lines that harbour intrinsic resistance to the mTKIs." (PMID 40781553, 2025). "Marker non-specificity (FAP, α-SMA, and PDGFRα/β) creates an on-target/off-tumor risk and, in sarcomas, can confuse stromal fibroblasts with malignant mesenchymal cells." (PMID 40940809, 2025). "Diagnosis and therapy for GISTs with neither the c-kit mutation nor the PDGFRA mutation require consultation with experts in this area or should be referred to hospitals specializing in GISTs and/or sarcomas." (PMID 38609732, 2024). "Specifically, PDGFRα appears to be uniquely overexpressed in SS relative to other sarcomas." (PMID 30909453, 2019). "Overexpression/activation of PDGFRα is a peculiar feature of SS among other sarcomas." (PMID 30909453, 2019). "However, in-depth knowledge about the presence and role of PDGFRA or other receptor tyrosine kinases in sarcoma cells or tumor microenvironment is still scarce." (PMID 31331295, 2019). "This present study is the first report describing the in vitro and in vivo efficacy of MGCD516, a novel, broad spectrum small molecule inhibitor that blocks a wide array of RTKs known to be amplified/overexpressed in sarcomas, including c-Kit, PDGFRβ, PDGFRα, c-Met, and Axl." (PMID 26675259, 2016). "It shows that expression of these ligands and receptors correlate with sarcoma patient outcomes and indicates that differential expression of the ligands may constitute relevant biomarkers of efficacy of PDGFRα antibodies in this heterogeneous family of diseases." (PMID 33524869, 2021). "Besides DFSP and PDGFRA-mutated GIST, the role of PDGFR and the according ligands in the biology of sarcomas remains unclear." (PMID 33524869, 2021). "A likely explanations for the strong PDGFR phosphorylation in KSHV-negative tumors could be the increased PDGFB ligand expression as well as the occurrence of oncogenic mutations that convey constitutive signaling, like those found in other PDGFRA-driven sarcomas such as GIST." (PMID 29985958, 2018). "Of note, CDK4 amplification in sarcoma cells was not susceptible to the PDGFRA target drug." (PMID 30598078, 2018). "Finally, as a standard of care drug in sarcoma and renal carcinoma pazopanib is dosed daily and would thus be likely to block any compensatory survival signaling through PDGFRα/PDGFRβ/FGFR, but not through c-MET or SRC-linked cytokine receptors." (PMID 28146421, 2017).
sarcoma (continued). "In sarcomas, many malignant cells themselves exhibit fibroblastic or myofibroblastic programs (e.g., α-SMA, FAP, PDGFRα/β, and vimentin)." (PMID 40940809, 2025). "PDGFRA amplification was also detected in lung squamous cell carcinoma (LUSC), LGG and sarcoma (SARC) in TCGA datasets." (PMID 36043552, 2023). "GIST constitutes the mainstay of theranostic application in sarcoma owing to the highly actionable targets KIT and PDGFRa." (PMID 37998367, 2023). "Since IMC-3G3, a monoclonal antibody against PDGFRα, has been approved by FDA in treating sarcoma patients, it will be interesting to know if ROR1-positive cancer cells are more sensitive to PDGFR inhibition." (PMID 31137681, 2019). "The expression levels of sunitinib targeted-kinases were measured by transcriptome sequencing for PDGFRA/B, KIT, RET, FLT1(VEGFR1), KDR (VEGFR2), and FLT4(VEGFR3) for patient cohort with EMC and other sarcoma histologies." (PMID 28423517, 2017). "Many sarcoma subtypes are characterized by potential driver kinases such as c-Met, IGF1-R, PDGFRα, and c-Kit." (PMID 26675259, 2016). "Additionally, among the seven cases of sarcoma with BCOR genetic alterations, six patients (85.7%) exhibited high expression of various markers (four for c-kit, six for PDGFRα, and two for VEGFR2)." (PMID 39534097, 2024). "The results presented here show that the overexpression of PDGFA might correlate with tumor aggressiveness in sarcoma: overexpression of PDGFA, a PDGFRα-specific ligand, was an independent adverse prognostic factor." (PMID 33524869, 2021). "The fact that PDGFRA also drives non-viral sarcomas highlights the importance of KSHV-dependent activation of PDGFRA in KS." (PMID 29985958, 2018). "A second limitation of our current analyses was that the detection of PDGFRA amplification among the intimal sarcomas could not be confirmed." (PMID 37395142, 2023). "A major breakthrough in targeted therapies for sarcomas is the recent FDA approval of an anti-PDGFRA therapeutic antibody to treat soft tissue sarcomas; which, as we show now for the case of viral sarcomagenesis with KS, are also oncogenically driven by ligand activation of the PDGFRA." (PMID 29985958, 2018). "PDGFRA is also an oncogenic driver in many non-viral sarcomas." (PMID 29985958, 2018). "This and the fact that PDGFRA drives non-viral sarcomas highlights the importance for KSHV-induced ligand-mediated activation of PDGFRA in KS sarcomagenesis and shows that this oncogenic axis could be successfully blocked to impede KS tumor growth." (PMID 29985958, 2018). "We neither did review of the radiology nor the pathology, but experienced sarcoma radiologists and pathologists at a major reference centre had already confirmed the diagnostic work-up at start of IM, including analyses of KIT and PDGFRA mutations that were found in all patients except three." (PMID 27999655, 2016). "Similarly in reference to the upregulation of PDGFRA/B in SS, a phase II study assessing imatinib efficacy in 10 sarcoma subtypes determined that it is not an active agent in SS." (PMID 22550415, 2012). "Other tyrosine kinase inhibitors, such as pazopanib (PDGFRα, PDGFRβ, and VEGFR inhibitor) and olaratumab (PDGFRα inhibitor), are already approved for sarcoma treatment, but their metabolic effects are not widely explored." (PMID 34201149, 2021).